LCN2 (lipocalin 2)
Diseases named in the same sentence as LCN2 in open-access papers (continued):
Sharing a sentence is not in itself a finding about the gene and the disease.
neurodegenerative disease (continued). "Thus, although a strong relationship between neurodegenerative disease progression and LCN2 levels in the CNS and blood have been reported, clinicians should use caution when using LCN2 levels as a clinical indicator of neurodegenerative disease progression." (PMID 33945675, 2021). "However, several studies have reported that LCN2 contributes to immune and inflammatory responses in the brain, eventually leading to the development of neurodegenerative diseases." (PMID 30761088, 2019). "Consequently, the effects of Lcn-2 on astrocytes may be bidirectional, and further research is needed to elucidate the specific mechanisms and regulatory factors governing the role of Lcn-2 in different neuroinflammatory and neurodegenerative diseases." (PMID 38533497, 2024). "Therefore, autophagy activation may be a promising therapeutic strategy to reduce the levels of secreted LCN2 and overcome neurodegenerative diseases." (PMID 37779143, 2023). "By reducing LCN2 levels in these astrocytes, it may be possible to convert them from a neurotoxic state to a neuroprotective one, potentially preventing neuronal cell death and the progression of neurodegenerative diseases." (PMID 37779143, 2023). "Lipocalin-2 (LCN2) is another inflammatory factor that is a target in regulating astrocytic reactions, and plays a detrimental role in the ischemic brain and neurodegenerative diseases." (PMID 33532143, 2021). "We therefore suggest that LCN2 may play an important role in neuroinflammation and oxidative stress induced by KA administration, and that LCN2 may be a potential therapeutic target against seizure-induced neuronal cell death and for other neurodegenerative diseases." (PMID 33445746, 2021).
infectious disease (16 papers, 2012 to 2025). A disorder directly resulting from the presence and activity of a microbial, viral, or parasitic agent in humans. "Lipocalin 2, a protein with a pivotal role in inflammatory responses and tissue damage, has been implicated in microbial invasion responses, suggesting its potential significance in infectious diseases." (PMID 39051782, 2024). "Additionally, some of these target genes, including SOD2, TNFAIP3, ARG1, SERPINB2, VLDLR, HSPA5, and LCN2, are associated with infectious diseases, suggesting that lncRNAs respond to PCV2 infection by regulating these genes." (PMID 30863688, 2019). "This suggests that the increased LCN2 level in children with ISS cannot be attributed to general bacterial infectious diseases." (PMID 35610759, 2022). "Research studies have revealed that LCN2 is also involved in infectious diseases." (PMID 35495713, 2022). "LCN2 is initially described as a beneficial signaling involved in infectious diseases, the role of LCN2 in the context of non-infectious conditions is less clear." (PMID 35413913, 2022). "This Janus face/dual role suggests that NGAL/LCN2 could be an important therapeutic target in chronic diseases, but caution must be exercised in the acute setting, especially during infectious diseases in which limiting the action of NGAL/LCN2 may be deleterious." (PMID 33510370, 2021).
liver (10 papers, 2014 to 2024). "In particular, the gastrointestinal tumors (ESCA, STAD, READ, and COAD) showed both the highest expression of LCN2 and the lowest expression of SLC22A17 compared to the related normal tissues." (PMID 36211450, 2022).
hematological malignancies (6 papers, 2014 to 2021). "Some very recent studies on different hematological malignancies reported that LCN2 protein strongly correlates with neutrophil count in PB and BM and differs with diagnosis." (PMID 34439364, 2021).
central nervous system diseases (5 papers, 2021 to 2025). "Although its functions within the peripheral system are most widely recognized, recent findings have revealed links between LCN2 and central nervous system diseases, as well as novel roles for LCN2 in neurons and glia." (PMID 33945675, 2021). "LCN2 is a pleiotropic molecule that is induced in central nervous system diseases." (PMID 40025014, 2025). "The expression level of LCN2 is quite low in normal adult brain and elevated in many central nervous system diseases, but the source of LCN2 could come from different lines of cells such as astrocyte, endothelia cell or neuron." (PMID 35413913, 2022).
urinary diseases (5 papers, 2014 to 2019). "Because the 24-kDa LCN2 protein was specifically observed in the urine of LPS-treated mice, we hypothesized that it may serve as a biomarker to identify urinary tract disorders." (PMID 26949374, 2016).
retinopathy (4 papers, 2015 to 2025). "Lipocalin 2 (LCN2 or NGAL), alone or complexed with MMP-9 (NGAL/MMP-9), is increased in several retinal disorders." (PMID 33214636, 2020).
adenocarcinoma (3 papers, 2008 to 2024). A common cancer characterized by the presence of malignant glandular cells. "Among these differentially expressed proteins, MCM6, LCN2 and PADI4 were highly expressed in SOL adenocarcinomas and the high expression of which was correlated with poor OS." (PMID 38182978, 2024).
brain diseases (3 papers, 2023 to 2024). "Long-term increases in Lcn-2 levels can make the brain more susceptible to various age-related brain diseases, potentially contributing to their development." (PMID 38533497, 2024). "Lcn2 is upregulated in several brain diseases and may contribute to neurodegeneration, promote cell death and inflammation." (PMID 37429840, 2023). "Therefore, Lcn-2 and astrocytes hold significant biological and clinical relevance in neuroinflammation, with Lcn-2 secreted by astrocytes potentially serving as a therapeutic target for various brain diseases with neuroinflammatory features." (PMID 38533497, 2024).
immune disorder (3 papers, 2020 to 2026). "LCN2, also known as neutrophil gelatinase-associated lipocalin (NGAL) or siderocalin, is upregulated in several immune disorders." (PMID 36613462, 2022).
intestinal disease (3 papers, 2023 to 2024). "Both calprotectin and lipocalin-2 are important fecal biomarkers associated with intestinal disease and inflammation." (PMID 38090485, 2023). "Further elucidation of the precise impact of the molecular regulation mechanism of LCN2 in ILC3s on the plasticity of ILC subpopulations will facilitate the optimization of targeted therapeutic strategies for ILC responses in intestinal diseases, which constitutes our forthcoming research focus." (PMID 39300068, 2024).
mental dysfunction (3 papers, 2013 to 2024). "To further demonstrate the causal relationship between hepatic LCN2 and mental dysfunction, we utilized an AAV vector carrying shRNA targeting the Lcn2 gene under the direction of the liver-specific promoter thyroxine-binding globulin (TBG)." (PMID 38589429, 2024). "In summary, distinct, region-specific neuronal changes produced by lipocalin-2 upon stress in the amygdala and hippocampus contribute to our understanding of adaptive and maladaptive processes that may underlie the development of stress-related psychiatric disorders." (PMID 23593384, 2013).
peripheral neuropathy (2 papers, 2021 to 2024). A disorder affecting the peripheral nervous system. "Many biomarkers are being studied currently, including TNF-like weak inducer of apoptosis (TWEAK), lipocalin 2 (LCN2, an iron transporter in innate immunity), S100B (strongly associated with peripheral neuropathy), and brain-derived neurotrophic factor (BDNF)." (PMID 38893713, 2024).
diseases of the reproductive system (1 paper, 2024). "Studies have clearly shown that aberrant expression of LCN2 is associated with a variety of disorders and malignancies, including several diseases of the reproductive system." (PMID 38645429, 2024).
muscular disorders (1 paper, 2024). "Further studies on how LCN2 functions under different bone diseases are of great importance, and precise role of LCN2 in the pathogenesis of metabolic and muscular disorders will pave the way for novel therapies targeting LCN2." (PMID 37326909, 2024).
skeletal diseases (1 paper, 2025). "This LCN2-mediated suppression of Wnt may impair osteocyte function and contribute to bone loss in skeletal diseases." (PMID 40343339, 2025).
LCN2 also shares sentences with these, for which no sentence is quoted: urinary tract infection (37 papers); heart disease (14); acute myocardial infarction (13); leptospirosis (13); systemic inflammatory response syndrome (12); rheumatoid arthritis (11); glomerulosclerosis (10); rhabdomyolysis (10); acute tubular necrosis (9); congenital heart disease (9); glomerulonephritis (9); hepatorenal syndrome (9); hydronephrosis (9); peritonitis (9); acute pyelonephritis (8); cardiac arrest (8); osteoarthritis (8); ST Elevation Myocardial Infarction (8); polycystic ovary syndrome (7); acute respiratory distress syndrome (6); Ascites (6); Hypoalbuminemia (6); ischemia reperfusion injury (6); nephrotic syndrome (6); autosomal dominant polycystic kidney disease (5); Shock (5); ankylosing spondylitis (4); aortic stenosis (4); benign tumors (4); collagenous colitis (4).
A further 337 diseases each share a sentence with LCN2 in 4 papers or fewer.